SNORA75 (Small nucleolar RNA SNORA75 )
Synonyms: LOC124900174
Gene: Small nucleolar RNA gene on chromosome 4 (79,843,102 to 79,843,228, forward strand). Ensembl gene ENSG00000212620.
Gene Ontology:
Biological process: RNA processing
Cellular component: nucleolus
Homologues: Orthologues: chimpanzee SNORA75 (99% identical), dog SNORA75 (79% identical), rat Snora75 (78% identical), mouse Gm25038 (75% identical), pig SNORA75 (75% identical), zebrafish SNORA75 (61% identical), mouse Gm56482 (59% identical), zebrafish SNORA75 (59% identical). Paralogues in human: SNORA75 (84% identical), SNORA75B (83% identical), SNORA75 (69% identical), SNORA75 (67% identical), SNORA75 (65% identical), SNORA75 (50% identical).
Diseases named in the same sentence as SNORA75 in open-access papers:
SNORA75 is named in the same sentence as 5 diseases in open-access papers, as found by Europe PMC text mining. Sharing a sentence is not in itself a finding about the gene and the disease. The quoted sentences say what the papers report.
colon cancer (1 paper, 2025). "Increased expression of snoRA38 and snoRA75 was observed in colon cancer metastasis to the liver." (PMID 41510246, 2025).
melanoma (1 paper, 2025). A malignant, usually aggressive tumor composed of atypical, neoplastic melanocytes. "SnoRA75 is among a group of 12 snoRNAs that show significant correlation with tumor microenvironment immune infiltration in melanoma." (PMID 41510246, 2025).
tumor (8 papers, 2018 to 2025). "The direct RNA targets of miR-24 include mitochondrial mt-Nd2 and Snora75, and their targeting leads to mitochondrial dysfunction and growth inhibition in tumour cells." (PMID 39183323, 2024). "Platelets inhibit tumor growth by transporting mir-24 to cancer cells targeting mt-Nd2 and Snora75, indicating that the regulatory effect of platelets on tumor growth is diverse." (PMID 39720182, 2024). "On the other hand, miR-24, another miRNA which is transferred from platelet MPs to tumor cells, constrains tumor growth by targeting mitochondrial mt-Nd2, and Snora75, resulting in mitochondrial dysfunction and tumor suppression." (PMID 30791448, 2019). "The inhibition of mt-Nd2 and Snora75 resulted in mitochondrial dysfunction and growth inhibition of tumor cells." (PMID 29670887, 2018). "However, some studies have indicated that certain natural PEVs can potentially affect tumour growth, such as PEVs that inhibit mitochondrial mt-ND2 and Snora75 (a non-coding small nucleolar RNA) by transferring miR-24, resulting in mitochondrial dysfunction and tumour cell growth inhibition." (PMID 39183323, 2024).
cancer (3 papers, 2020 to 2025). A tumor composed of atypical neoplastic, often pleomorphic cells that invade other tissues. "SnoRNAs with elevated expression in GSC and GBM lines (snoRA38, snoRA51, snoRA71, and snoRA75) have been previously implicated in cancer development." (PMID 41510246, 2025).
SNORA75 also shares sentences with these, for which no sentence is quoted: glioblastoma (1 paper).